RNU6-70P (RNA, U6 small nuclear 70, pseudogene)
Synonyms: RNU6-70
Gene: Small nuclear RNA gene on chromosome 13 (27,343,687 to 27,343,746, reverse strand). Ensembl gene ENSG00000252247.
Homologues: Orthologues: guinea pig U6 (90% identical), macaque U6 (87% identical). Paralogues in human: U6 (98% identical), RNU6-29P (97% identical), RNU6-1 (95% identical), RNU6-11P (95% identical), RNU6-12P (95% identical), RNU6-13P (95% identical), RNU6-16P (95% identical), RNU6-17P (95% identical), RNU6-18P (95% identical), RNU6-2 (95% identical), RNU6-25P (95% identical), RNU6-32P (95% identical), and 1288 more.